Y_RNA (Y RNA )
Gene: Miscellaneous RNA gene on chromosome 3 (165,122,713 to 165,122,823, reverse strand). Ensembl gene ENSG00000200052.
Homologues: Orthologues: chimpanzee Y_RNA (99% identical). Paralogues in human: RNY1P5 (80% identical), Y_RNA (80% identical), RNY1 (79% identical), Y_RNA (78% identical), Y_RNA (77% identical), Y_RNA (76% identical), RNY1P11 (75% identical), Y_RNA (75% identical), RNY1P8 (74% identical), Y_RNA (74% identical), Y_RNA (73% identical), RNY1P13 (72% identical), and 90 more.